CCL5 (C-C motif chemokine ligand 5)
Diseases named in the same sentence as CCL5 in open-access papers (continued):
Sharing a sentence is not in itself a finding about the gene and the disease.
intestinal infection (1 paper, 2017). "To determine whether the altered chemokine response in T. gondii-infected P2X7R−/− mice was also true for another small intestinal infection, we also analysed epithelial CCL5 in T. spiralis infection." (PMID 27559003, 2017).
invasive candidiasis (1 paper, 2012). "In separate experiments, induction of Ccr1 and its ligands Ccl3, Ccl5, Ccl6, Ccl7, Ccl8 and Ccl9 by invasive candidiasis was examined in greater detail in mice injected with 1.25×105 CFU of C. albicans, which causes ∼80% mortality by day 14 post-infection." (PMID 22916017, 2012).
invasive ductal carcinoma (1 paper, 2017). "Moreover, several studies have shown a positive correlation between the number of infiltrating macrophages in invasive ductal carcinoma and the expression of CCL2, CSF-1, and CCL5." (PMID 28881599, 2017).
ischemia reperfusion injury (1 paper, 2017). Adverse functional, metabolic, or structural changes in ischemic tissues resulting from the restoration of blood flow to the tissue (reperfusion), including swelling; hemorrhage; necrosis; and damage from free radicals. "CCL5/RANTES, a chemoattractant for myeloid cells, is induced by hepatic ischemia/reperfusion injury (IRI)." (PMID 28623253, 2017).
Kawasaki disease (1 paper, 2021). A rare inflammatory disease characterized by an acute febrile, systemic, self-limiting, medium-vessel vasculitis primarily affecting children. "Our study shows that we can distinguish normal samples from Kawasaki disease samples based on the infiltration of immune cells, and that CXCL8, CCL5, CCR7, CXCR3, and CCR1 may play important roles in the development of Kawasaki disease." (PMID 33188570, 2021).
kidney cancer (1 paper, 2024). Primary or metastatic malignant neoplasm involving the kidney. "In our research, utilizing bioinformatics analysis, we suggested that CCL5 advances the malignancy of kidney cancer CTCs." (PMID 39227943, 2024).
kidney transplant (1 paper, 2013). A surgical procedure in which one or both kidneys from a donor are implanted into a recipient. "During kidney transplant rejection intrarenal RNA expression of Th1-associated ligands CXCL10 and CCL5 have been documented, also increased urinary chemokines CXCL9 and CXCL10 were found during acute rejection compared to stable recipients." (PMID 23717673, 2013). "Th1 cells preferentially express the chemokine receptors CCR5 and CXCR3 migrating towards CCL5 and CXCL10 which are expressed by TECs and present during kidney transplant rejection." (PMID 23717673, 2013).
lumbar disc degeneration (1 paper, 2019). "CCL5/RANTES was described as a key factor secreted from the IVD and involved in the recruitment of MSCs and then was identified as an IVD degeneration marker in the plasma of patients with lumbar disc degeneration." (PMID 31827537, 2019).
macular degeneration (1 paper, 2021). Loss of vision in the central portion of the retina (macula), secondary to retinal degeneration. "Median CCL3 and CCL5 concentrations were significantly decreased in the macular degeneration group compared with controls (p < 0.001) as well as when a cutoff value comparison was used." (PMID 34869411, 2021).
malignant hypertension (1 paper, 2021). Severe hypertension that is characterized by rapid onset of extremely high blood pressure and hypertension-mediated organ damage. "CC-chemokine ligand 5 (CCL5) and C-X-C motif chemokine ligand 3 (CXCL3) showed no induction under malignant hypertension." (PMID 34528115, 2021).
metastasis (1 paper, 2022). The spread or migration of cancer cells from one part of the body (where they first appeared) to another. "In addition, linear regression analysis was carried out for CCL5 levels in serum and tumor tissue to explore the relationship between lymph node metastasis and CCL5." (PMID 36033472, 2022).
metastatic prostate carcinoma (1 paper, 2020). A carcinoma that arises from the prostate gland and has spread to other anatomic sites. "This study provides a novel rationale for developing TAMs/CCL5 as a potential molecular target for PCSCs elimination and metastatic prostate cancer prevention." (PMID 32300100, 2020).
microencephaly (1 paper, 2022). "RANTES/CCL5 expression was 4-5-fold higher in human placentas from babies with microencephaly, compared to ZIKV infected placentas from without microencephaly." (PMID 36315601, 2022).
Miscarriage (1 paper, 2014). A pregnancy that ends at a stage in which the fetus is incapable of surviving on its own, defined as the spontaneous loss of a fetus before the 22th week of pregnancy. "In conclusion, we have found plasma concentrations of the cytokines IL-1β, IL-6 and IL-10, and the chemokines, CXCL8, CCL2, CCL5, CCL7, CX3CL1 cannot predict subsequent miscarriage." (PMID 24699265, 2014).
mucolipidosis type IV (1 paper, 2025). A lysosomal disease characterized by psychomotor delay, progressive visual impairment, and achlorhydria. "Furthermore, the expression level of Ccl5 (RANTES) was increased in Hexa-/-Neu3-/- mice, similar to mouse models of the Niemann Pick type C (Npc1-/-), Gaucher (Gba-/-) and mucolipidosis type IV (Mcoln1-/-), and this increase was reduced after KD and PG treatments." (PMID 40019557, 2025).
mucopolysaccharidosis (1 paper, 2023). A group of autosomal recessive or X-linked inherited lysosomal storage disorders affecting the metabolism of mucopolysaccharides, resulting in the accumulation of mucopolysaccharides in the body. "PPS reduces serum and tissue levels of TNFα, MIP-1α and RANTES/CCL5 in Mucopolysaccharidosis (MPS) type VI rats." (PMID 36986536, 2023).
muscular dystrophy (1 paper, 2009). Muscular dystrophy (MD) refers to a group of more than 30 genetic diseases characterized by progressive weakness and degeneration of the skeletal muscles that control movement. "In this regard, we have recently reported a marked upregulation of CCR1 and two of its major ligands, RANTES (CCL5) and MIP-1α (CCL3), in the diaphragms of muscular dystrophy (mdx) mice and demonstrated a relationship with the degree of muscle infiltration by mononuclear inflammatory cells." (PMID 19421418, 2009).
nephrotic syndrome (1 paper, 2016). A collection of symptoms that include severe edema, proteinuria, and hypoalbuminemia; it is indicative of renal dysfunction. "Urinary excretion of interleukin-18 (IL-18)/CXCL8, MCP-1/CCL2, and RANTES/CCL5 was not different in an analysis of patients with steroid-resistant or steroid-sensitive nephrotic syndrome." (PMID 26989679, 2016).
neuralgia (1 paper, 2015). "In our clinical neuralgia cases, the hypothesis of RANTES/CCL5 as a source of pain has persisted for years, so the experimental time limit for RANTES/CCL5 exposure on the opioid receptors is irrelevant." (PMID 26170877, 2015).
onchocerciasis (1 paper, 2022). Onchocerciasis is a form of filariasis, caused by the parasitic worm Onchocerca volvulus, transmitted by the black fly. "Similarly, ivermectin treatment in onchocerciasis patients induced a significant increase in CCL5/RANTES and eotaxin expression in the skin post treatment, which resulted in an increase of skin eosinophils 24h after treatment." (PMID 36389745, 2022).
orbital disease (1 paper, 2026). "Notably, it reduced key signs of orbital disease, including brown adipose tissue expansion, CCL5-positive immune cell infiltration, CD4+ T-cell infiltration and the presence of F4/80+ macrophages." (PMID 41837138, 2026).
otitis media (1 paper, 2009). Inflammation of the anatomical structures of the middle ear, which is most often caused by an infectious process. "CCL5, also known as RANTES, is 18 kb from the linkage peak, and has been previously associated with otitis media." (PMID 19728873, 2009).
ovarian dysfunction (1 paper, 2023). The inability of the ovaries to function. "Previous studies suggested that the progression of ovarian dysfunction is associated with immune dysregulation induced by an abnormal proportion of CD8+ T cells and upregulation of CCL5 and IFN-γ." (PMID 37223018, 2023).
peripheral vascular disease (1 paper, 2013). Any disorder affecting blood flow through the veins or arteries outside of the heart. "Furthermore, expression and secretion of CCL-2, CCL-5 and CX3CL-1 by human coronary artery endothelial cells as well as monocytes was inhibited by preincubation with rHDL, and rHDL (CSL111; 80 mg/kg) infused in patients with peripheral vascular disease decreased CD11b on neutrophils." (PMID 23967171, 2013).
prostate adenocarcinoma (1 paper, 2025). "While previous studies in prostate adenocarcinoma have shown that CCL5 upregulates androgen receptor signaling and contributes to enzalutamide resistance—an effect that may be mitigated by maraviroc—our current study focuses on the role of the unique context of cisplatin treatment in NEPC." (PMID 41152972, 2025).
relapsing-remitting MS (1 paper, 2022). "However, CCL5 levels were lower in stable relapsing-remitting MS and progressive MS than in MS relapse and below the detection limit in patients with the non-inflammatory neurological disease." (PMID 35632621, 2022).
renal sclerosis (1 paper, 2025). "Consistent with improved blood BUN levels, Nutlin 3b relieved hyalination, a sign of renal sclerosis, SASP (Tnfα, Cxcl1, Ccl5) and the senescent marker p16Ink4a in aged kidneys." (PMID 41392167, 2025).
resistant hypertension (1 paper, 2022). "Low plasmatic levels of the chemokine RANTES/CCL5 was the most significant result associated with RDN response and may help to identify the best candidates among patients with true resistant hypertension." (PMID 35330342, 2022).
Rickettsiosis (1 paper, 2022). A group of infectious diseases that is caused by Rickettsia. "While no increased expression of CCL-5 was detected in TG rickettsiosis, the expression of CCL-5 and also CXCL-10 was elevated in patients with Mediterranean spotted fever (MSF) caused by R. conorii and RMSF caused by R. rickettsii." (PMID 35543881, 2022).
Rotavirus infection (1 paper, 2017). Infection with any of the rotaviruses. "Of interest, several IFN inducible genes (OAS1, MX1, IL18, IITP3, TAP1, and RSAD2) as well as several cytokines and chemokines (CCL5, CXCL10, CXCL11, IL8, and CCL15) were upregulated by rotavirus infection." (PMID 28210256, 2017).
Seizure (1 paper, 2022). A seizure is an intermittent abnormality of nervous system physiology characterized by a transient occurrence of signs and/or symptoms due to abnormal excessive or synchronous neuronal activity in the brain. "It was confirmed, in a KA-induced seizure model, that CCL5 was implicated in the recruitment of inflammatory cells in the CNS." (PMID 35326336, 2022).
serous carcinoma (1 paper, 2022). "And, CCL5 is important for the recruitment and activation of lymphocytes, so we proposed that ACKR2_CCL5 may weaken the recruitment and activation of lymphocytes, contributing to the metastasis of primary high-grade serous carcinoma." (PMID 35935940, 2022). "Metastasis of high-grade serous carcinoma may be related to the interaction between high expression of ACKR2 chemokine receptor and cytokines such as CCL5." (PMID 35935940, 2022).
serous ovarian cancer (1 paper, 2022). "Furthermore, an inverse association for genetically proxied concentrations of Beta-Chemokine RANTES (RANTES/CCL5) in relation to serous ovarian cancer (0.70, 0.57 to 0.85, p = 3.8 × 10−4) was found, which was based on a single instrumental variable, hence no sensitivity analyses were performed." (PMID 35012533, 2022).
skin Paget disease (1 paper, 2023). "In skin Paget disease, the cells release soluble RANKL, improving the secretion of CCL5, CCL17, and CXCL10 from RANK+ M2 polarized TAMs, suggesting that Paget cells can modulate the microenvironment landscape by the stimulation of TAMs." (PMID 37958292, 2023).
skin rashes (1 paper, 2023). "Promotion of CCL5 expression is expected to contribute to the exacerbation of EGFR inhibitor-induced skin rashes." (PMID 38092882, 2023).
T cell deficiency (1 paper, 2022). "However, the retroviral expression of CCL5 in BM progenitors or a brief ex vivo stimulation of HSCs with CCL5 resulted in T cell deficiency but the expansion of myeloid progenitors." (PMID 36148240, 2022).
Thrombocytosis (1 paper, 2021). Increased numbers of platelets in the peripheral blood. "Subsequent thrombocytosis increases arterial deposition of the powerful myeloid cell-attracting chemokine CCL5 (RANTES), which ultimately promotes the development of atherosclerotic lesions." (PMID 34977044, 2021).
tongue cancer (1 paper, 2013). A malignant neoplasm affecting the tongue. "In tongue cancer the CCL5/CCR5 axis stimulated increased cell migration and the expression of MMP9 has been proposed to be mediated through NF-kappaB signaling pathways." (PMID 24204919, 2013). "To explore the importance of CCL5/CCR5 axis in the spread of tongue cancer, we performed a 3D invasion study with SAS and HSC-3 OTSCC cells with reduced CCR5 expression and with function-blocking antibody against CCL5." (PMID 24204919, 2013). "This suggests that CCL5 might affect more the number of superficially disseminating invasive cells than the total invasive capacity of tongue carcinoma cells." (PMID 24204919, 2013). "Next, to evaluate the importance of CCL5 expression in patient tumor samples for diagnostics of tongue cancer, histological sections representing different stages of dysplastic lesions and tongue carcinomas from human patients were stained with anti-CCL5 antibody." (PMID 24204919, 2013).
toxoplasmosis (1 paper, 2024). A parasitic disease contracted by the ingestion or fetal transmission of toxoplasma gondii. "So, it is likely that the upregulated inflammatory genes, such as Ccl5, Ccl3, Ccl7, Ccr5, and Cxcr3, could be the key factors that cause mouse reproductive organ damage, and then contribute to the tragic pregnancy outcomes of toxoplasmosis." (PMID 39006750, 2024).
Uterine leiomyoma (1 paper, 2017). The presence of a leiomyoma of the uterus. "Using total RNA prepared from our second panel of 26 matched specimens, we confirmed that ESR1, SOX18, CCL5, and PCDH10 but not CALCRL are differentially expressed in uterine leiomyomas or that levels of their expression vary by menstrual phase." (PMID 28637297, 2017).
vaginal infection (1 paper, 2022). "CCL5 specifically seems to drive NK cell recruitment during HSV2 vaginal infection, as loss of CCL5 leads to a decrease in infiltrating NK cells and increased viral loads, indicating the importance of NK cells in HSV2 immunity." (PMID 36211447, 2022).
Varicose veins (1 paper, 2025). Enlarged and tortuous veins. "The second CCL5-related TF, EBF1, is implicated in blood pressure and inflammation, and its genetic variants were previously associated with varicose veins in a large-scale genetic study." (PMID 41009355, 2025).
vasculitis (1 paper, 2020). "Then, we found the expression of related inflammatory cytokines IL-6 and CCL5 were significantly decreased after treatment, it may further reduce the damage of vasculitis." (PMID 33133061, 2020).
Ventriculomegaly (1 paper, 2012). An increase in size of the ventricular system of the brain. "Interestingly, in this same study, elevated concentrations of the chemokine Regulated upon Activation, Normal T-cell Expressed, and Secreted (RANTES, also known as CCL5) was associated with reduced risk of both ventriculomegaly and echolucent lesions." (PMID 22530124, 2012).
Vestibular schwannoma (1 paper, 2024). A vestibular schwannoma (also known as acoustic neuroma, acoustic neurinoma, or acoustic neurilemoma) is a benign, usually slow-growing tumor that develops from the VIIIth cranial nerve supplying the inner ear. "In addition to CCL2, the examination of our cell culture supernatants of VS primary cultures suggests that vestibular schwannoma cells produce the cytokines CCL5, CCL18, TGFB1, and GDF15, which has not yet been investigated for VSs." (PMID 39272860, 2024).
Waldenstrom macroglobulinemia (1 paper, 2014). "In B-cell malignancy, Waldenstrom Macroglobulinemia (WM), CCL5 modulated IL6 expression through the JAK/STAT signaling pathway." (PMID 25072326, 2014).
tumor (2,039 papers, 1999 to 2026). "Deletion of Ccl5 from miR-146a-deficient mice returned tumor growth and the aberrant myeloid cell populations to wild-type levels." (PMID 41718085, 2026). "By up-regulating the expression of IRF5 and down-regulating CCL5, it promotes the transformation of M2 tumor-associated macrophages, reprograms the tumor microenvironment immunology, and achieves substantial reduction in postsurgical pancreatic tumor regrowth." (PMID 40868764, 2025). "Several studies have found that the expression of CCL5 is associated with the degree of T cell infiltration within tumors, indicating its potential role in lipid metabolism in the tumor microenvironment." (PMID 40070829, 2025). "Immune modulatory molecules, such as CCL2 and CCL5, which recruit tumor-associated macrophages, and adhesion molecules ICAM1 and VCAM1, which facilitate immune cell trafficking, were also included." (PMID 40652770, 2025). "The RANTES/CCL5 chemokine is implicated in tumor progression, as well as in immune and inflammatory responses." (PMID 40076291, 2025). "The analysis revealed that higher CCL5 expression was associated with higher tumor grades and advanced stages of GC." (PMID 40884261, 2025). "Empirical investigation has demonstrated a significant association between elevated CCL5 levels in tumor specimens and an augmented susceptibility to neoplasm relapse within a 5-year period following therapeutic intervention." (PMID 40297849, 2025). "It is also known that CCL5 expression induces tumour‐associated fibroblasts in the tumour microenvironment, thereby promoting tumour cell proliferation, and that high CCL5 expression is generally associated with poor prognosis." (PMID 40500939, 2025). "High tumor CCL5 expression is associated with greater CD8 + T cell infiltration and improved patient prognosis." (PMID 41444923, 2025). "This association likely stems from CCL5’s role in orchestrating the leukocyte population within the tumor." (PMID 41445742, 2025). "Further, CCL5 blocking significantly rescued the inhibition of tumor growth and was associated with a significant decrease in the infiltration of both NK and CD8 T cells." (PMID 40611330, 2025). "Whereas the anti-tumor immune responses can be inhibited due to the declined secretion of CCL5 by autophagic tumor cells, which can cause a recruitment of NK cells." (PMID 40064873, 2025). "CCL5 expression by gastric cancer is correlated with tumor progression; a possible mechanism behind this association is the disproportional accumulation of CD4+ and CD8+ T cells, plus selective apoptosis of CD8+ T cells in the tumor." (PMID 38786066, 2024). "Intra-tumor injection of E. coli MG1655 reprogramed tumor-associated macrophages into M1 phenotype that produce abundant CCL5, together facilitating tumor infiltration of adoptively transferred T cells." (PMID 40124706, 2024). "The overexpression of CCL2 and CCL5 is associated with tumor metastasis and a poor prognosis in patients." (PMID 38468244, 2024). "In the central nervous system (CNS), mouse Nf1 optic gliomas require the elaboration of Ccl5 from tumor-associated monocytes (TAMs)." (PMID 38308315, 2024). "The relationship between IDO1 and marker genes of tumor-associated macrophages (TAMs; CCL5, CD68, and IL10), M1 (IRF5, NOS2, and PTGS2), and M2 (CD163, VSIG4, and MS4A4A) macrophages was analyzed." (PMID 39351094, 2024). "Among other notable DEGs, PD-L1+ clusters were also defined by high expression of many transcripts encoding for chemokines that have been shown to be released by suppressive tumor-associated neutrophils such as Ccl2, Ccl3, Ccl4, Ccl5, Ccl12, Ccl17, and Cxcl16." (PMID 39392875, 2024). "Tumor cells expressing CCL5 were associated with worse DFS, overall survival (OS), and relapse-free survival (RFS), especially in more advanced stages." (PMID 39409924, 2024).